YBX3 (Y-box binding protein 3)
Description:
Binds to the GM-CSF promoter. Seems to act as a repressor. Also binds to full-length mRNA and to short RNA sequences containing the consensus site 5'-UCCAUCA-3'. May have a role in translation repression (By similarity).
Synonyms: CSDA; DBPA; ZONAB; CSDA1
Tractability: PROTAC: ubiquitination databases record sites on it; its protein half-life has been measured.
Target class: Transcription factor
Gene: Protein-coding gene on chromosome 12 (10,699,077 to 10,723,388, reverse strand). Ensembl gene ENSG00000060138.
Subcellular location: Cytoplasm; Nucleus
Subcellular location (Human Protein Atlas): Cytosol
Gene Ontology:
Molecular function: protein binding; RNA binding; mRNA 3'-UTR binding; nucleic acid binding; small GTPase binding; DNA binding; ribonucleoprotein complex binding; RNA polymerase II transcription regulatory region sequence-specific DNA binding
Biological process: cellular hyperosmotic response; cellular response to tumor necrosis factor; negative regulation of intrinsic apoptotic signaling pathway in response to osmotic stress; negative regulation of necroptotic process; 3'-UTR-mediated mRNA stabilization; positive regulation of cytoplasmic translation; regulation of gene expression; negative regulation of transcription by RNA polymerase II
Cellular component: cytosol; bicellular tight junction; cytoplasm; nucleus; perinuclear region of cytoplasm; synapse
Genetic constraint (gnomAD): Loss-of-function variants: 27 observed, 36.79 expected, observed/expected ratio (o/e) 0.73, 90% interval 0.54 to 1.01. The upper end of that interval is the gene's LOEUF score, 1.01, which puts it in group 4 of 6, group 1 being the genes least tolerant of losing a copy. Missense variants: 480 observed, 445.59 expected, observed/expected ratio (o/e) 1.08, 90% interval 1 to 1.16. Synonymous variants: 184 observed, 157.72 expected, observed/expected ratio (o/e) 1.17, 90% interval 1.03 to 1.32.
Homologues: Orthologues: chimpanzee YBX3 (100% identical), macaque YBX3 (99% identical), pig YBX3 (93% identical), dog YBX3 (92% identical), rabbit YBX3 (88% identical), rat Ybx3 (87% identical), mouse Ybx3 (86% identical), guinea pig YBX3 (77% identical), tropical clawed frog ybx3 (45% identical), Caenorhabditis elegans cey-1 (27% identical). Paralogues in human: YBX1 (55% identical), YBX2 (40% identical), LIN28B (18% identical), LIN28A (16% identical).
Diseases named in the same sentence as YBX3 in open-access papers:
YBX3 is named in the same sentence as 83 diseases in open-access papers, as found by Europe PMC text mining. Sharing a sentence is not in itself a finding about the gene and the disease. The quoted sentences say what the papers report.
breast cancer (8 papers, 2008 to 2025). A primary or metastatic malignant neoplasm involving the breast. "Closely associated with cell death mechanisms like autophagy, YBX3 also influences chemoresistance in breast cancer by affecting autophagy-related pathways." (PMID 41213937, 2025). "In breast cancer, NGR1 can regulate the expression of CCND2 and YBX3 to inhibit breast cancer angiogenesis and slow down the progression of breast cancer, but NGR1’s ferroptosis-associated neighborhood has not been reported." (PMID 38885076, 2024).
Arthritis (7 papers, 2013 to 2025). Inflammation of a joint. "In CEACAM1, YBX3 and SLC6A8, all three genes were found to be overexpressed in patients with arthritis associated with fever." (PMID 38243323, 2024).
colon carcinoma (6 papers, 2019 to 2023). "Another research also suggested that RBP YBX3 was associated with tumour immune evasion via different mechanisms involving T-cell exclusion in different cancer types (especially in colon cancer) and by the tumour infiltration of immune cells." (PMID 36895014, 2023). "Increasing evidences have shown that YBX3 is aberrantly upregulated in hepatocellular carcinoma, pancreatic cancer, colon cancer and lung cancer." (PMID 37612524, 2023). "Among various cancers, especially colon cancer, YBX3 is more related than HEIH expression to the clinical features and prognosis of subgroups." (PMID 36059530, 2022). "We identified the pathogenic roles of YBX3 and its regulatory lncRNA HEIH in various cancers and investigated their effects on tumor progression in colon cancer." (PMID 36059530, 2022). "IHC staining of the TMA showed that the expression of YBX3 was significantly greater in colon cancer tissues than in paracancerous tissues, and the trend was more evident in the cytoplasm of glandular cells and colonic epithelial cells." (PMID 36059530, 2022). "After visualizing the scRNA-seq data, we analyzed data from colon cancer chips, such as 146771 and 136394, and found that YBX3 was highly expressed in various cell types, especially monocytic series, malignant cells, and CD8 T cells." (PMID 36059530, 2022). "The results showed that a higher expression of the YBX3 gene indicates primary colon cancer with high lymph node stage (≥1), metastasis status, serum CEA level (≥5 ng/ml), lymphatic invasion, and/or residual tumor after surgery (≥1), all with P <0.05." (PMID 36059530, 2022). "However, glioma and colon cancer patients with a higher YBX3 expression tended to benefit more from chemotherapy than those with a lower YBX3 expression, with P-values of 0.065 and 0.011 for glioma and colon cancer, respectively." (PMID 36059530, 2022). "Moreover, for patients suffering from colon cancer with a higher degree of malignancy, a higher expression of YBX3 predicts worse prognosis, which demonstrates that it is associated with high-risk clinical features." (PMID 36059530, 2022). "This study strongly suggests that lncRNA-HEIH/YBX3 is a pancancer immune-oncogenic system and could serve as a biomarker for diagnosis and prognosis and as a therapeutic target, especially in colon cancer." (PMID 36059530, 2022). "We performed a qPCR analysis of cDNA samples from 12 patients from our hospital with distinct stages of colon cancer, and we found that, as the tumor stage progressed, HEIH expression decreased, while YBX3 expression rose." (PMID 36059530, 2022). "Hence, in this study, we explored the effect of the RBP YBX3 on various genes involved in multiple hallmarks of cancer and the effect of its upstream lncRNA HEIH on oncogenesis and progression across cancers, particularly their role in colon cancer." (PMID 36059530, 2022). "Furthermore, its expression in colon cancer is clinically significant, and there is an obvious negative regulatory association between HEIH and YBX3." (PMID 36059530, 2022). "Both YBX3 and lncRNA HEIH regulate the therapeutic response through certain common molecular mechanisms, but the role of the tumor regulation system composed of lncRNA-HEIH/YBX3 in the tumor microenvironment (TME) of diverse tumors, especially in colon cancer, has not been fully investigated." (PMID 36059530, 2022).
colorectal cancer (6 papers, 2017 to 2025). A primary or metastatic malignant neoplasm that affects the colon or rectum. "In this study, we found that symplekin primarily localizes to the nuclei of cultured dedifferentiated colorectal cancer cells, and nuclear symplekin showed higher phosphorylation and binding affinity with YBX3 than its membrane fraction." (PMID 28630428, 2017).
hepatocellular carcinoma (6 papers, 2018 to 2025). A malignant tumor that arises from hepatocytes. "This study establishes TTC36 as a pivotal tumor suppressor in hepatocellular carcinoma that orchestrates a previously unrecognized TTC36/YBX3/SPRED1 signaling axis which suppresses Ras/MAPK pathway to constrain tumor proliferation." (PMID 41208883, 2025). "In hepatocellular carcinoma (HCC), YBX3 promotes tumor growth by enhancing cell survival under stress conditions through the regulation of oxidative stress responses and metabolic reprogramming." (PMID 41213937, 2025).
gastric cancer (5 papers, 2015 to 2025). A primary or metastatic malignant neoplasm involving the stomach. "An elevated expression of YBX3 in gastric cancer has been linked to advanced clinicopathological features, shorter survival time, and poor prognosis, which was consistent with the findings of Xiang and colleagues." (PMID 37418046, 2023). "Previous evidence indicates that YBX3 upregulation promotes gastric cancer pathogenesis by increasing cell invasion and tumor chemoresistance." (PMID 33229623, 2020). "Furthermore, in gastric cancer (GC), YBX3 regulates Hepatocyte Growth Factor (HGF)-mediated cellular proliferation and metastasis." (PMID 41213937, 2025).
clear cell Renal Cell Carcinoma (4 papers, 2014 to 2026). "The objective of the current study was to investigate the role of YBX3 in the prognosis, immune infiltration, and progression of clear cell renal clear cell carcinoma (ccRCC)." (PMID 37418046, 2023). "Y box binding protein 3 (YBX3) is an oncogene in clear cell renal cell carcinoma (ccRCC)." (PMID 42111157, 2026).
bladder cancer (3 papers, 2022 to 2025). "Moreover, in this study it was observed that, in some cancer cohorts, such as bladder cancer, a lower YBX3 expression was associated with a greater infiltration of CTLs." (PMID 36059530, 2022). "Furthermore, we observed that lower expression levels of YBX3 were associated with improved clinical outcomes for ICB therapy (PDL1 or PD1) in bladder cancer and glioblastomas and consequently longer survival times (upper row)." (PMID 36059530, 2022). "Some studies have found that YBX3 can promote the proliferation of breast cancer cells, inhibit the proliferation of kidney and gastric cancer cells, and modulate the function of tight junction (TJ) proteins in bladder cancer." (PMID 36059530, 2022). "The lncRNA BLACAT3 recruits Y-box binding protein 3 (YBX3) into the nucleus, synergistically increases NCF2 transcription and promotes bladder cancer angiogenesis and blood metastasis by activating the downstream NF-κB signalling pathway." (PMID 40665344, 2025).
glioma (3 papers, 2022 to 2025). A benign or malignant brain and spinal cord tumor that arises from glial cells (astrocytes, oligodendrocytes, ependymal cells). "Single-gene knock-out and overexpression studies of CHEK2, YBX1, and YBX3 in multiple glioma cell lines revealed that these proteins positively regulate each other’s expression." (PMID 40161682, 2025). "Therefore, CHK2-YBX1&YBX3 hub targeting in combination with immune checkpoint blockade therapies in gliomas is warranted." (PMID 40161682, 2025).
lung carcinoma (3 papers, 2017 to 2023). "It is worth mentioning that, for tumors that occur in the upper body, such as ACC, HNSC, and lung cancers (including LUSC and LUAD), a higher YBX3 expression indicates a worse prognosis in terms of OS, DSS, and PFI, all with P <0.05." (PMID 36059530, 2022).
melanoma (3 papers, 2020 to 2024). A malignant, usually aggressive tumor composed of atypical, neoplastic melanocytes. "Conversely, a higher YBX3 expression was associated with more benefits of CTLA4 ICB in melanoma patients and thus a prolonged survival period." (PMID 36059530, 2022). "Moreover, in melanoma cohorts, a higher expression of YBX3 was associated with a higher level of CTLs, indicating an interplay with CTL exclusion (lower row)." (PMID 36059530, 2022).
leukemia (2 papers, 2021 to 2025). A malignant (clonal) hematologic disorder, involving hematopoietic stem cells and characterized by the presence of primitive or atypical myeloid or lymphoid cells in the bone marrow and the blood. "Using strategies that target YBX3 or pre-BCR-related modules in pre-BCRd-related leukemias may also further improve outcomes in patients with these subsets of high-risk B-ALL." (PMID 34824268, 2021).
liver cancer (2 papers, 2020 to 2025). An epithelial or non-epithelial malignant neoplasm that arises from the liver. "At the cellular level, YBX3 and CH25H were highly expressed in liver cancer cell lines, and ABCA6, PLIN5, AMACR, AKR1D1, CYP27A1, CYP46A1 were highly expressed in liver cancer cell lines in CCLE." (PMID 32627826, 2020). "Unlike the mechanism in liver cancer, where circPIAS1 inhibits ferroptosis through the miR-455-3p/NUPR1 axis, YBX3 directly targets SLC7A11 and destabilizes it through lysosomal degradation." (PMID 41213937, 2025).
Obesity (2 papers, 2024 to 2025). Accumulation of substantial excess body fat. "In vivo, YBX3 overexpression improves diet-induced metabolic dysfunction, while its knockdown suppresses thermogenesis and exacerbates obesity phenotypes." (PMID 40725470, 2025). "Next, we fed the KD and control mice a 60% kcal HFD to investigate the impact of Ybx3 knockdown in diet-induced obesity and glucose dysfunction." (PMID 39481849, 2024). "BAT-specific loss of Ybx3 dampens thermogenesis and exacerbates diet-induced obesity in mice, while overexpression of Ybx3 promotes thermogenesis and confers protection against diet-induced metabolic dysfunction." (PMID 39481849, 2024). "•YBX3 confers protection against diet-induced obesity and metabolic dysfunction." (PMID 39481849, 2024). "Having observed the critical role of Ybx3 in brown adipocyte differentiation and thermogenesis, we asked whether Ybx3 overexpression confers protection against diet-induced obesity and metabolic dysregulation." (PMID 39481849, 2024). "YBX3 facilitates BAT fueling BCAA to boost thermogenesis and energy expenditure, which protects against obesity and metabolic dysfunction." (PMID 39481849, 2024). "Our findings unveiled the YBX3-mediated linking between BCAA metabolism and BAT differentiation and thermogenesis, providing a potential therapeutic approach against obesity and related metabolic dysfunction." (PMID 39481849, 2024). "Thus, YBX3 could be a promising therapeutic target for obesity." (PMID 39481849, 2024).
ovarian carcinoma (2 papers, 2022 to 2023). A malignant neoplasm originating from the surface ovarian epithelium. "In breast and ovarian cancer cohorts, higher YBX3 expression was significantly associated with chemotherapy resistance." (PMID 37418046, 2023). "We observed that among breast and ovarian cancer cohorts, a higher YBX3 expression was significantly associated with resistance to chemotherapies (both P <0.01)." (PMID 36059530, 2022).
autoimmune disease (1 paper, 2024). A disorder resulting from loss of function or tissue destruction of an organ or multiple organs, arising from humoral or cellular immune responses of the individual to their own tissue constituents. "YBX3 is less studied at present, especially in autoimmune diseases." (PMID 38243323, 2024).
B-cell acute lymphoblastic leukemia (1 paper, 2021). A neoplasm of lymphoblasts committed to the B-cell lineage, typically composed of small to medium-sized blast cells. "In addition, we identify the RNA-binding protein YBX3 as a marker of pre-B cell differentiation and correlate Ybx3 expression with outcomes in patients with B cell acute lymphoblastic leukemia." (PMID 34824268, 2021).
bone metastasis (1 paper, 2020). Transfer of a neoplasm from its primary site to bones. "More importantly, among the OS-SEs, we identified two bone metastasis-related ASEs (ABCA6-43162-AT and PLIN5-46808-AT) co-expressing with SF YBX3 and pathway of primary bile acid biosynthesis." (PMID 32627826, 2020).
COVID-19 (1 paper, 2023). A disease caused by infection with severe acute respiratory syndrome coronavirus 2. "By excluding 4 genes, YBX3, RBM38, ANCA, and BLVRB, with opposite expression trends, we found that when compared to control samples, practically all of these genes showed persistently high expression in AMI and COVID-19." (PMID 38022594, 2023).
Duchenne muscular dystrophy (1 paper, 2020). Duchenne muscular dystrophy (DMD) is a neuromuscular disease characterized by rapidly progressive muscle weakness and wasting due to degeneration of skeletal, smooth and cardiac muscle. "In the end, nevertheless, YBX3 and UTRN are not directly associated with IPF, it has been reported the involvement of these coding RNAs in claudin-mediated cell proliferation regulation, which is impaired in lung diseases and Duchenne Muscular Dystrophy (DMD) fibrosis, respectively." (PMID 33233868, 2020).
epilepsy (1 paper, 2021). A brain disorder characterized by episodes of abnormally increased neuronal discharge resulting in transient episodes of sensory or motor neurological dysfunction, or psychic dysfunction. "Bioinformatics analysis revealed that the effects of AS3MT on epilepsy likely involved multiple targets including MTHFR, GSTM1, CYP17A1, NT5C2, YBX3, CNNM2, CACNB2, and TRIM26." (PMID 34899152, 2021). "The effects of AS3MT on epilepsy might involve multiple targets including CNNM2, CACNB2, TRIM26, MTHFR, GSTM1, CYP17A1, NT5C2, and YBX3." (PMID 34899152, 2021).
Hyperinsulinemia (1 paper, 2024). An increased concentration of insulin in the blood. "In contrast, we observed the additive effect of hyperinsulinemia and JAKi on the cell cycle-controlling genes CDKN2D/p19, EIF2S3B, GREM2, and YBX3." (PMID 39768214, 2024).
Intellectual disability (1 paper, 2024). "We focused on YBX1 and YBX3 because they are expressed in the adult nervous system and found that several large CNVs involving either the YBX1 or YBX3 loci, as well as one rare missense YBX3 variant, are present in individuals with neurological symptoms including intellectual disability." (PMID 39423228, 2024). "The most common symptom reported in individuals with CNV deletions including the YBXs is intellectual disability, as 37.5% of individuals with CNV deletions containing YBX1 and 80% of individuals with CNV deletions in YBX3 have intellectual disability." (PMID 39423228, 2024).
kidney cancer (1 paper, 2022). Primary or metastatic malignant neoplasm involving the kidney. "To date, studies of YBX3 have been reported only for breast, liver, and kidney cancers." (PMID 36059530, 2022).
metastatic tumor (1 paper, 2025). "The results indicated that, compared to primary tumor tissues, the expression levels of PTBP3, RBFOX1, SRRM2, YBX3, and QKI were significantly higher in metastatic tumor tissues." (PMID 40270362, 2025).
osteoarthritis (1 paper, 2023). A noninflammatory degenerative joint disease occurring chiefly in older persons, characterized by degeneration of the articular cartilage, hypertrophy of bone at the margins and changes in the synovial membrane. "Taken together, our findings provide strong evidence for a regulatory role for the circSERPINE2/YBX3/PCNA/p21 axis in MSC senescence and the therapeutic potential of si-circSERPINE2 in alleviating aging-associated syndromes, such as osteoarthritis." (PMID 37831180, 2023).
renal fibrosis (1 paper, 2023). A final common manifestation of a wide variety of chronic kidney diseases characterized by glomerulosclerosis and tubulointerstitial fibrosis. "Further investigation of the key markers of renal fibrosis showed a reduced induction of both tenascin-C and αSMA in Ybx3 knockouts, as well as collagen I and III." (PMID 37408260, 2023).
skin squamous cell carcinoma (1 paper, 2021). A carcinoma arising from the squamous cells of the epidermis. "In skin squamous cell carcinoma (SCC), YBX3 was high expression in SCC patient tissues and cells, and promoted the proliferation, migration, and invasion of SCC cells depending on the NF-κB pathway." (PMID 33816248, 2021).
tubulointerstitial nephritis (1 paper, 2023). "To further investigate the role of DbpA in kidney disease progression, we examined a model of tubulointerstitial nephritis, namely unilateral ureter obstruction (UUO), in wild-type and MSY4-deficient mice, hereafter referred to as Ybx3-deficient mice." (PMID 37408260, 2023).
infection (35 papers, 2008 to 2026). The state of being infected such as from the introduction of a foreign agent such as serum, vaccine, antigenic substance or organism. "For example within 24 hours of infection, host Bcar1 (Breast cancer anti-estrogen resistance-1, also known as p130CAS), Ybx3 (Y box binding protein 3, also known as ZONAB), Mras (Ras related protein) and Cstf2 (Cleavage stimulation factor 2, also known as Cstf-64) increased in abundance." (PMID 28452683, 2017).